DNMT3A (DNA methyltransferase 3 alpha)
Diseases named in the same sentence as DNMT3A in open-access papers (continued):
Sharing a sentence is not in itself a finding about the gene and the disease.
tumor (continued). "According to public databases, our data strongly suggest CDK6, DNMT3A and DNMT3B as direct targets of miR-29a-3p: disallowed tumor-suppressive function of this miRNA may stimulate tumorigenesis by promoting cell cycle progression and altering de novo methylation of the genome." (PMID 27829219, 2016). "This promoter hypomethylation either results from a failure to maintain established methylation patterns during tumor progression due to a lack of Dnmt3a or from an increased proliferation of cancer cells resulting from transformation but not necessarily linked to Dnmt3a maintenance activity." (PMID 27677595, 2016). "Interestingly, we observed the development of CLL with no signs of myeloproliferation, thus suggesting that Dnmt3a tumor suppressor function in prevention of CLL is autonomous to the hematopoietic system." (PMID 27677595, 2016). "While not directly tumor promoting, increased cell-to-cell variation and mosaicism resulting from inactivation of DNMT3a might be a substrate for clonal selection of rare pre-neoplastic cells." (PMID 26046760, 2015). "Thus, the distinct immune landscapes of DNMT3A- and GMPS-driven tumors in liver versus pancreas can be rationalized by the different nutrient pathways that each enzyme controls and by organ-specific stromal contexts that dictate how those metabolites sculpt the tumor immune micro-environment." (PMID 41465346, 2025). "Our findings demonstrate for the first time that DNMT3A and DNMT3B overexpression may contribute to radiotherapy failure, and their inhibition might be a promising radiosensitizing strategy, mainly in the treatment of patients with metastatic or recurrent RMS tumours." (PMID 34831178, 2021). "The levels of DNMTs, especially those of DNMT3B, DNMT3A, and DNMT3L, are often increased in various cancer tissues and cell lines, which may partially account for the hypermethylation of promoter CpG-rich regions of tumor suppressor genes in a variety of malignancies." (PMID 24822169, 2014). "Most importantly, the expression of TAT was significantly decreased in tumor cells with a high expression of DNMT3A and DNMT3B, and there was an obvious negative correlation between TAT and DNMT3A/3B." (PMID 39334853, 2024). "In addition, others have hypothesized a similar carcinogenesis model in which DNMT3A and DNMT3B are specifically recruited during tumor initiation and promotion, with a subsequent downregulation of their expression, whereas DNMT1 is involved in tumor progression." (PMID 37894317, 2023). "In a statistical study with TNM staging and history of chronic pancreatitis, DNMT3A and DNMT3B, but not DNMT1 expression, correlated with tumor size." (PMID 24822169, 2014). "Two of the genomic alterations found enriched in older patient tumors may be attributed to age-related clonal hematopoiesis (DNMT3A, TET2), which may or may not be relevant to the actual tumor biology." (PMID 38975340, 2024). "In contrast, DNMT3a was decreased in the castrated mice (P < 0.05), and DNMT1 and DNMT3b were both significantly decreased in the combination group (P < 0.01 and P < 0.05, respectively), which was not consistent with the tumor sizes in the different groups." (PMID 24885368, 2014). "However, miR-148a expression was inversely correlated with the expression of DNMT1 (ρ = − 0.31, P = 0.04), whereas miR-148b expression showed negative correlation with the expression of DNMT3A (ρ = − 0.38, P = 0.02) and DNMT3B (ρ = − 0.33, P = 0.03) in tumor tissues from 42 NSCLC patients." (PMID 36959680, 2023). "In addition, no apparent changes in DNMT3A and DNMT3B were observed in tumor cells." (PMID 32154082, 2020).
cancer (393 papers, 2006 to 2026). A tumor composed of atypical neoplastic, often pleomorphic cells that invade other tissues. "Not only do these data indicate increasing degrees of emergency hematopoiesis with age but also confirm an age-associated decline in DNMT3A, even in cancer patients." (PMID 39236155, 2024). "Overexpression of DNMT3A is associated with oncogenesis in multiple cancers via epigenetic silencing of pivotal tumor suppressor genes and distortion of T-cell function." (PMID 37847338, 2024). "Putative DNMT3A and DNMT3B somatic driver mutations are also widespread in cancer but the majority of these are uncharacterised with the exception of DNMT3A mutations in acute myeloid leukeamia (AML)." (PMID 39446312, 2024). "Another frequent DNMT3A cancer mutation R736H is located at the FF interface and is reported to make this interface more flexible and stimulate DNMT3A activity in wildtype:mutant hetero-complexes." (PMID 39446312, 2024). "Here, we examined the binding of Dnmt3a-CD and M.SssI to the G4 structure formed by the purine-rich strand of the promoter region of the cancer-associated c-MYC gene (27fG4)." (PMID 38203216, 2023). "In our analysis, both maintenance methylation (DNMT1, DNMT2) and de novo methylation (DNMT3a, DNMT3b) were found to be significantly associated with pan-cancer, resulting in the methylation of CEP55 at positions cg25827255, cg25314624, and cg04026927." (PMID 37887301, 2023). "Mutations in the DNMT3A gene are often observed in hematological malignancies, but less frequently in other cancers." (PMID 34214250, 2022). "In disease context, DNMT3a has been described to be overexpressed or mutated in various carcinomas and correlates with the down-regulation of caspase-8 in these same scenarios." (PMID 36112666, 2022). "We demonstrated an association between the TET2/DNMT3A mutations and growth inhibition of cancer cells by T-dCyd treatment across 17 human solid tumor cell lines." (PMID 34039392, 2021). "By contrast, the role of previous cancer treatment in TRMN emergence in TRMN with TET2/DNMT3A mutations is uncertain." (PMID 34423258, 2021). "This study aims to investigate TET2/DNMT3A mutations and antitumor activity of a novel epigenetic agent in multiple human cancer cell lines and animal models." (PMID 34039392, 2021). "DNMTs expression especially for DNMT3A/3B was closely associated with AML among various human cancers." (PMID 32597790, 2020). "This study revealed the conserved features of genomic methylation in cancer cells, DNMT3A deficiency increased the instability of the whole genome, confirming the role of DNMT3A in maintaining the methylation pattern of cancer DNA." (PMID 32751889, 2020). "DNMT3a mediated DNA hypermethylation suppressed gene expression and has been associated with many cancer developments." (PMID 33234142, 2020). "Here, we comprehensively profile the genomic landscape of 42 benign and malignant tumors across 13 individuals from four multigenerational families and discover recurrent mutations in epigenetic modifiers DNMT3A and BCOR in 29% of benign tumors." (PMID 31624251, 2019). "High expression of DNMT3A or DNMT3B has been observed in a large number of specimens from cancer patients, and increased DNMT3A expression is implicated in hepatocellular carcinogenesis." (PMID 31615043, 2019). "DNMT3A mutations are frequently observed in hematological malignancies and occur in a comparable range of lymphoid and myeloid disorders." (PMID 30635552, 2019). "According to the CBioPortal cancer clinical research database, DNMT3A missense mutations account for 1.7% of all known DNMT3A abnormalities (215 studies, 56,243 patients)." (PMID 31861499, 2019). "DNMT1 mutations in colon tumors and DNMT3A mutations in hematological malignancies have been observed in the cancer genome." (PMID 28127428, 2017).
cancer (continued). "Ultimately, these exposures led to potentially detrimental hypomethylation of genomic DNA, a hallmark of genomic instability and cancer, through a miR29a-DNMT3a regulatory pathway that is conserved across 500 million years of evolution." (PMID 29203905, 2017). "Recently, a number of studies have investigated the association between DNMT3A variants and cancer risk, and proposed a putative functional variant (rs1550117) in the 448bp upstream of the transcription start site of DNMT3A gene promoter." (PMID 28423585, 2017). "To determine the effects of loss of Dnmt3a on cancer methylomes we next performed WGBS on DNA isolated from Dnmt3aΔ/Δ CLL and PTCL cells." (PMID 27677595, 2016). "To determine the effects of Dnmt3a loss on the cancer methylome, we next performed WGBS on DNA isolated from Dnmt3aΔ/Δ PTCL cells." (PMID 27690235, 2016). "We propose a working model that UHRF1/2 safeguards the fidelity of DNA methylation and suggests that UHRF1/2 overexpression is likely a causal factor for widespread DNA hypomethylation in cancer via suppressing DNMT3A." (PMID 27462454, 2016). "This is a requirement for understanding their roles in cellular transformation, because mutations detected in cancer can inactivate or impair DNA methylation (for example, DNMT3A mutations) or DNA demethylation (for example, TET2 or IDH mutations)." (PMID 25632305, 2015). "A strong case can be made that DNMT3A is an oncogene, as it is overexpressed in several cancers, depletion results in decreased proliferation and metastasis, and 5-aza-dC causes apoptosis through direct inhibition of DNMT3A." (PMID 24622842, 2014). "DNMT3A mutations in cancer have been reported in all three domains, with most occurring in the catalytic domain, including the R882 mutation (60%)." (PMID 24622842, 2014). "Cellular DNA methylation is orchestrated by three distinct DNA methyltransferases, DNMT1, DNMT3a and DNMT3b, and aberrant expression of these DNMTs has been causally linked to atypical DNA methylation levels in human cancers." (PMID 24252647, 2013). "Amongst their targets are DNMT3A and 3B-methyltransferases, whose levels can increase because of the loss of miR-29, causing CpG island hypermethylation and cancer." (PMID 22384141, 2012). "Our results uncover a novel function of this de novo methyltransferase in cancer, as Dnmt3a deficiency results in loss of methylation in large active chromatin domains." (PMID 23284304, 2012). "The number of hypomethylated windows was strongly increased when Dnmt3aKO tumors were compared to normal lung tissue (n = 2383), which indicated a pronounced effect of the Dnmt3a mutation on the cancer epigenome." (PMID 23284304, 2012). "Our study thus defines the role of Dnmt3a in maintaining DNA methylation patterns and provides a paradigm for understanding the effects of DNMT3A mutations on human cancer methylomes." (PMID 23284304, 2012). "To date, DNMT3A represents the only DNA methyltransferase gene that has been found to carry genetic mutations in human cancers." (PMID 23284304, 2012). "While Dnmt1 is considered a biological target involved in cancer development its close relative Dnmt3a, investigated in this study, has been linked to both cancer development and mental performance and health." (PMID 21510884, 2011). "Future studies of other DNMT3A sequence variants and their biologic function are also needed in order to understand the role of DNMT3A polymorphisms in determining the risk of cancer." (PMID 20128888, 2010). "This highlights the need for long-term follow-up and bone marrow assessment in RDD patients harboring DNMT3A mutations to clarify whether these alterations contribute to disease pathogenesis, cancer predisposition, or represent incidental findings." (PMID 40406258, 2025).
cancer (continued). "Since EMT is a hallmark of castration resistance, cancer stem cells generation, chemoresistance and worse prognosis for prostate cancer, targeting DNMT3A may be of great therapeutic value in improving the prognosis of advanced and metastatic prostate cancer." (PMID 37273004, 2023). "In addition to the oncohistone mutations that disrupt the interplay between H3K36me2/me3 and DNAme, recurrent mutations of H3K36 KMTs and DNMT3A are also identified in various types of cancer." (PMID 37602556, 2023). "The overexpression of DNMT3a has also been shown to be associated with several cancers." (PMID 36112666, 2022). "The enhanced catalytic activity of DNMT3A is associated with cancer development and progression." (PMID 36551768, 2022). "Among the DNMTs, mutations in DNMT3A have been reported to be most frequent in cancer." (PMID 36091786, 2022). "Recent cancer genome sequencing studies revealed mutations in many epigenetic modifiers that are associated with various cancers, such as DNMT3A in acute myeloid leukemia, IDH1/2 in glioblastoma, CREBBP/EP300 in small-cell lung cancer and ARID1A in gastric cancer." (PMID 35973998, 2022). "However, mutations of DNMT3A have been broadly detected in various cancers, especially in adult hematologic malignancies." (PMID 33299888, 2020). "Among DNMT1, DNMT3A and DNMT3B, mutations in DNMT3A have been reported most frequently in cancer." (PMID 32751889, 2020). "The targeted NGS panel used in this study, Oncomine Pan‐Cancer, covers the most commonly detected mutations from solid tumors; however, it does not cover the genes that are commonly associated with hematopoietic stem cells, such as DNMT3A, TET2, and ASXL1." (PMID 32449983, 2020). "To determine whether susceptibility to hematologic malignancy was affected by the cooperation of Kmt2a-PTD with DNMT3A-WT/MT, we monitored mice up to 10 months." (PMID 32015320, 2020). "Similarly, a new quinoline-based molecule, MC3353, can also inhibit the activity of DNMT1 and DNMT3A to reverse hypermethylation caused by cancer." (PMID 32751889, 2020). "DNA methyltransferase 3A (DNMT3A) has been recognised as a key element of epigenetic regulation in normal development, and the aberrant regulation of DNMT3A is implicated in multiple types of cancers, especially haematological malignancies." (PMID 29717263, 2018). "DNMT3A has been implicated in the dysregulation of several cellular processes in cancers." (PMID 29717263, 2018). "Therefore, compared with the G allele, the rs1550117 A allele would decrease SP1 binding affinity, and then leads to the increased expression of DNMT3A, which finally increases cancer susceptibility." (PMID 28423585, 2017). "Future research will investigate whether drugs that inhibit the breakdown of fats could help to treat cancers in which the Dnmt3a and Dnmt3b proteins are mutated or less active." (PMID 28425913, 2017). "However, once formed, Dnmt3a-deficient tumors grew, and progressed to carcinomas with the same kinetics and proportions, respectively, as their wild-type counterparts." (PMID 28425913, 2017). "Thus, negative regulation of DNMT3A by overexpressed UHRF1/2 in cancers is likely to be a general mechanism for cancer-associated DNA hypomethylation." (PMID 27462454, 2016). "This could be a consequence of genetic alterations in enzymes regulating epigenetic patterns, such as gene mutations found in human myeloid malignancies, including DNMT3a, TET2, IDH1, IDH2, EZH2, or ASXL1." (PMID 24944583, 2014). "Some polymorphisms of the DNMT3A gene may regulate gene expression, influence its enzymatic activity and may contribute to susceptibility to cancer." (PMID 24667323, 2014). "In addition, overexpression of either DNMT3A or DNMT3B is associated with tumorigenesis depending on cancer types in humans." (PMID 23613894, 2013). "Cancer-associated mutations of DNMT3A are associated with poor prognosis, which suggests that they might functionally contribute to the disease phenotype." (PMID 23284304, 2012).
cancer (continued). "This is consistent with the recent observation that hypomethylation in gastric CAFs could not be attributed to any difference in mRNA levels of DNMT1, DNMT3a, or DNMT3b between normal and cancer-associated myofibroblasts." (PMID 22984426, 2012). "However, human tumors are characterized by a complex pattern of genetic mutations and the specific effects of DNMT3A mutations on the cancer methylome have yet to be identified." (PMID 23284304, 2012). "Strikingly, this domain structure was strongly altered in Dnmt3aKO tumors and chromosomes were characterized by uniform hypomethylation suggesting that Dnmt3a may protect the genome from global cancer-associated hypomethylation." (PMID 23284304, 2012). "In the present work, we want to determine whether a single nucleotide polymorphism (SNP) in DNMT3A promoters contributes to its increased expression and whether functional SNP is substantially associated with cancer susceptibility." (PMID 20128888, 2010). "However, few studies have reported on the possible association of cancer susceptibility with DNMT3A, another active de novo methyltransferase in mammals." (PMID 20128888, 2010). "We hypothesized that the genetic variants of DNMT3A that are responsible for regulating the methylation status of other genes are associated with an increased risk of cancer." (PMID 20128888, 2010). "The clinical significances of DNMT3A mutation allele ratio might be explained by cancer biology." (PMID 31291961, 2019). "Therefore, identification of functional variants in DNMT3A gene and analysis of their effects may lead to a better understanding of their impact on DNMT3A gene expression and individual susceptibility to cancer." (PMID 28423585, 2017). "However, mutations in the human DNMT3A gene have been detected in various cancers, suggesting that the enzyme might also be relevant for DNA methylation in adult tissues and in tumors." (PMID 23284304, 2012). "We hypothesized that polymorphisms of DNMT3A promoter are associated with the risk of cancer." (PMID 20128888, 2010). "miR-148a targets DNMT1 and reduces its levels in cancer, whereas miR-29 Family is known as a repressor of DNMT3A and DNMT3B expression by directly targeting their mRNAs." (PMID 39996888, 2025). "The hypoxia-induced genome-wide DNA demethylation in these two types of cancer cells also appeared to require DNMT3A." (PMID 40764968, 2025). "The striatal clone contained additional cancer-associated driver mutations (NRAS G12D and DNMT3A splice donor variants)." (PMID 40610627, 2025). "The primary function of DNMT1 is maintaining CpG methylation status during cell division (maintaining the cancer stem cell status), while DNMT3A and DNMT3B are predominantly involved in de novo methylation." (PMID 40507223, 2025). "To better reveal the functions of DNMT3A in cancer occurrence and development, in this study, we mutated HEK293T cells using the CRISPR/Cas9 technology and successfully created a DNMT3A knockout cell line with homozygous frameshift deletion in both alleles." (PMID 41450820, 2025). "DNMT3A occupies a central position in the origin and progression of a broad spectrum of cancers, with its impact being particularly pronounced in AML." (PMID 40675967, 2025). "Following recruitment, the chromatin-bound DNMT3A preferably demethylates CpGs in its vicinity including the HRE CpG under the relatively high Ca2+ ion concentration of cancer cells." (PMID 40764968, 2025). "In the following, we provide the first direct evidence that one of the DNA methyltransferases, DNMT3A, is required for hypoxia-induced transcriptional activation of the EMT-associated gene TWIST1 in cell lines of three different cancer cell types." (PMID 40764968, 2025). "The role of DNMT3a is broader as it can affect the methylation of multiple regions in the genome, plays a role in multiple cancer types and is essential for hematopoietic stem cell differentiation." (PMID 41159936, 2025).